CD81 (CD81 molecule)
Description:
Structural component of specialized membrane microdomains known as tetraspanin-enriched microdomains (TERMs), which act as platforms for receptor clustering and signaling. Essential for trafficking and compartmentalization of CD19 receptor on the surface of activated B cells. Upon initial encounter with microbial pathogens, enables the assembly of CD19-CR2/CD21 and B cell receptor (BCR) complexes at signaling TERMs, lowering the threshold dose of antigen required to trigger B cell clonal expansion and antibody production. In T cells, facilitates the localization of CD247/CD3 zeta at antigen-induced synapses with B cells, providing for costimulation and polarization toward T helper type 2 phenotype. Present in MHC class II compartments, may also play a role in antigen presentation. Can act both as positive and negative regulator of homotypic or heterotypic cell-cell fusion processes. Positively regulates sperm-egg fusion and may be involved in acrosome reaction (By similarity). In myoblasts, associates with CD9 and PTGFRN and inhibits myotube fusion during muscle regeneration (By similarity). In macrophages, associates with CD9 and beta-1 and beta-2 integrins, and prevents macrophage fusion into multinucleated giant cells specialized in ingesting complement-opsonized large particles. Also prevents the fusion of mononuclear cell progenitors into osteoclasts in charge of bone resorption (By similarity). May regulate the compartmentalization of enzymatic activities. In T cells, defines the subcellular localization of dNTPase SAMHD1 and permits its degradation by the proteasome, thereby controlling intracellular dNTP levels. Also involved in cell adhesion and motility. Positively regulates integrin-mediated adhesion of macrophages, particularly relevant for the inflammatory response in the lung (By similarity). (Microbial infection) Acts as a receptor for hepatitis C virus (HCV) in hepatocytes. Association with CLDN1 and the CLDN1-CD81 receptor complex is essential for HCV entry into host cell. (Microbial infection) Involved in SAMHD1-dependent restriction of HIV-1 replication. May support early replication of both R5- and X4-tropic HIV-1 viruses in T cells, likely via proteasome-dependent degradation of SAMHD1. (Microbial infection) Specifically required for Plasmodium falciparum infectivity of hepatocytes, controlling sporozoite entry into hepatocytes via the parasitophorous vacuole and subsequent parasite differentiation to exoerythrocytic forms.
Synonyms: TAPA1; TSPAN28; TAPA-1; S5.7; CVID6
Tractability: Small molecule: a structure with a bound ligand is known; a high-quality ligand is known. Antibody: UniProt places it where antibodies can reach, with high confidence; its Gene Ontology location is reachable by antibodies, with high confidence; UniProt predicts a signal peptide or a membrane-spanning region; the Human Protein Atlas places it where antibodies can reach. PROTAC: ubiquitination databases record sites on it; its protein half-life has been measured; a small molecule that binds it is known.
Target class: Surface antigen
Gene: Protein-coding gene on chromosome 11 (2,376,166 to 2,397,802, forward strand). Ensembl gene ENSG00000110651.
Subcellular location: Cell membrane; Basolateral cell membrane
Subcellular location (Human Protein Atlas): Plasma membrane; Cytosol
Pathways (Reactome):
Immune System: Immunoregulatory interactions between a Lymphoid and a non-Lymphoid cell; Regulation of Complement cascade
Gene Ontology:
Molecular function: cholesterol binding; integrin binding; MHC class II protein binding; MHC class II protein complex binding; protein binding; transferrin receptor binding; virus receptor activity
Biological process: CD4-positive, alpha-beta T cell costimulation; endoplasmic reticulum to Golgi vesicle-mediated transport; humoral immune response mediated by circulating immunoglobulin; immunological synapse formation; macrophage fusion; positive regulation of adaptive immune memory response; positive regulation of B cell proliferation; positive regulation of B cell receptor signaling pathway; positive regulation of CD4-positive, alpha-beta T cell proliferation; positive regulation of MAPK cascade; positive regulation of protein catabolic process in the vacuole; positive regulation of receptor clustering; positive regulation of T cell activation via T cell receptor contact with antigen bound to MHC molecule on antigen presenting cell; positive regulation of T cell receptor signaling pathway; positive regulation of T-helper 2 cell cytokine production; positive regulation of transcription by RNA polymerase II; protein localization to lysosome; protein localization to plasma membrane; regulation of protein stability; cellular response to low-density lipoprotein particle stimulus; myoblast fusion involved in skeletal muscle regeneration; osteoclast fusion; positive regulation of inflammatory response to antigenic stimulus; receptor internalization; regulation of macrophage migration; and 2 more
Cellular component: basal plasma membrane; basolateral plasma membrane; extracellular exosome; focal adhesion; immunological synapse; membrane; plasma membrane; tetraspanin-enriched microdomain; vesicle; cytoplasm
Genetic constraint (gnomAD): Loss-of-function variants: 9 observed, 22.37 expected, observed/expected ratio (o/e) 0.4, 90% interval 0.24 to 0.7. The upper end of that interval is the gene's LOEUF score, 0.7, which puts it in group 2 of 6, group 1 being the genes least tolerant of losing a copy. Missense variants: 237 observed, 286.42 expected, observed/expected ratio (o/e) 0.83, 90% interval 0.74 to 0.92. Synonymous variants: 128 observed, 119.02 expected, observed/expected ratio (o/e) 1.08, 90% interval 0.93 to 1.25.
Gene-disease validity (ClinGen):
ClinGen rates the evidence that CD81 causes each of these diseases.
immunodeficiency, common variable, 6 (autosomal recessive): Limited.
Homologues: Orthologues: dog CD81 (97% identical), chimpanzee CD81 (94% identical), rat Cd81 (93% identical), guinea pig CD81 (93% identical), mouse Cd81 (92% identical), macaque CD81 (91% identical), pig CD81 (89% identical), tropical clawed frog cd81 (71% identical), zebrafish cd81a (65% identical), zebrafish cd81b (60% identical), Caenorhabditis elegans tsp-9 (28% identical). Paralogues in human: CD9 (44% identical), TSPAN2 (40% identical), TSPAN8 (31% identical), TSPAN5 (28% identical), TSPAN18 (27% identical), TSPAN11 (27% identical), TSPAN17 (27% identical), CD82 (26% identical), TSPAN1 (26% identical), TSPAN9 (26% identical), CD151 (26% identical), TSPAN14 (26% identical), and 20 more.
Diseases named in the same sentence as CD81 in open-access papers:
CD81 is named in the same sentence as 199 diseases in open-access papers, as found by Europe PMC text mining. Sharing a sentence is not in itself a finding about the gene and the disease. The quoted sentences say what the papers report.
hepatoma (65 papers, 2005 to 2025). "HCV was adapted via passaging an HCV infectious virus clone several times in human hepatoma cells, mouse liver cells, and eventually primary mouse hepatocytes deficient in innate immunity and ectopically expressing human occludin and human CD81." (PMID 40242309, 2025). "The tetraspanin CD81 is one of the main entry receptors for Hepatitis C virus, which is a major causative agent to develop liver cirrhosis and hepatocellular carcinoma (HCC)." (PMID 38357447, 2024). "In hepatoma cells, the endogenous function of CD81 is less well defined, although it has been implicated in cell migration and proliferation upon tissue wounding." (PMID 29677132, 2018). "Comparison of the absolute CAPN5 abundance with the enrichment from the CD81 IP suggests that a large fraction of CAPN5 is associated with CD81 in human hepatoma cells." (PMID 30024968, 2018). "Knockout of CD81 almost completely abrogated susceptibility of human hepatoma cells to HCV.Taken together we find that the CD81 interaction partners CAPN5 and CBLB are HCV host dependency factors." (PMID 30024968, 2018). "CD81 is an essential HCV host factor as silencing of CD81 expression in hepatoma cells inhibits HCV entry while CD81 expression in HCV-resistant hepatoma cell lines confers susceptibility to HCV entry." (PMID 23704981, 2013). "Immunoblot analysis of all four HCV entry factors (CLDN1, OCLN, SRBI, and CD81) in HFLC showed levels of expression comparable to those of the HCV-susceptible hepatoma Huh-7.5." (PMID 22144107, 2011). "HepG2 cells, a CD81 negative human hepatoma cell line, transfected and expressing CD81 were less susceptible to HCVpp infection than Huh7 cells, a CD81 positive human hepatoma cell line, although expressing higher levels of surface CD81." (PMID 19643019, 2009). "We aimed to resolve this issue by using HCVcc mutants defective in CD81 binding and cell entry, and hepatoma-derived cell lines deficient in CD81 expression." (PMID 19088272, 2009). "Moreover, CAPN5 and CBLB appear to be strongly associated with the CD81 complex as their total abundance in human hepatoma cell lysates was comparably low as quantified by intensity based absolute quantification (iBAQ)." (PMID 30024968, 2018). "With regard to cancer pathogenesis, in several tumors, CD81 has been shown to play a role in cancer cell migration and progression; in particular, decreased expression of CD81 is associated with metastasis in hepatocellular carcinoma and with the growth and survival of gastric cancer." (PMID 25915404, 2015). "In addition, ectopic expression of murine CD81 (mCD81) in CD81-deficient hepatoma cells restored to some extent permissivity to HCVpp and HCVcc." (PMID 24509809, 2014). "Here, we identify CD81 as one of few surface proteins that are downregulated in HCV expressing hepatoma cells, discovering a functional role of CD81 beyond mediating HCV entry." (PMID 38357447, 2024). "We enriched for endogenous CD81 from hepatoma cells or primary human hepatocytes (PHH) with CD81-specific antibodies and performed additional immunoprecipitations with anti-HA antibodies from hepatoma cells ectopically expressing HA-tagged CD81." (PMID 37967063, 2023). "To this end, we used the cell culture-derived human hepatoma cell clone Lunet N#3 that lacks endogenous expression of CD81 and cells overexpressing human CD81 (Lunet N#3 hCD81)." (PMID 35612284, 2022). "Next, we silenced endogenous CD81 in human hepatoma cells (Huh-7.5) and infected these with the CHIKV ECSA genotype." (PMID 35612284, 2022). "Alterations in CD81 surface expression levels has previously been reported in clonal populations of hepatoma cells." (PMID 34209751, 2021). "As expected, CD81 (with an HH/HC ratio of 14.7) was found to be among the most downregulated genes in hepatoma cells." (PMID 34268141, 2021).
hepatoma (continued). "It should be noted that P. berghei is strictly CD81-dependent for invasion of the mouse cell line Hepa 1.6 but CD81-independent when human hepatoma cell lines are used." (PMID 34268141, 2021). "This study aims to investigate the relationship between KLF4 and CD9/CD81 in hepatocellular carcinoma (HCC)." (PMID 32350244, 2020). "JFH-1 replicates robustly in human hepatoma cell lines that express the viral entry factor CD81, allowing measurement of both HCV RNA levels and HCV infectivity." (PMID 30696822, 2019). "While we discovered CAPN5 as CD81 interaction partner in hepatoma cells and primary human hepatocytes, we included CBLB as a hit from the STRING network analysis." (PMID 30024968, 2018). "In total, we identified 183 significant proteins in co-immunoprecipitations from hCD81 expressing hepatoma cells using an antibody targeting the CD81 LEL." (PMID 30024968, 2018). "Twenty-three CD81 interactors found in primary human hepatocytes overlapped with the set of 29 hepatoma cell interactors." (PMID 30024968, 2018). "Here, we used P. yoelii as surrogate system for the human pathogenic P. falciparum, since both species share the requirement for CD81 and P. yoelii can infect human hepatoma cell lines, while P. falciparum only infects primary cells." (PMID 30024968, 2018). "Wildtype and HA-tagged CD81 were expressed at the cell surface and in intracellular compartments comparable to endogenous CD81 in Huh-7.5 human hepatoma cells." (PMID 30024968, 2018). "The 10 novel hits together with the 23 hits from the first overlap analysis resulted in 33 high confidence CD81 interactors in primary hepatocytes and hepatoma cells." (PMID 30024968, 2018). "Here we mapped 33 host protein interactions of CD81 in primary human liver and hepatoma cells using high-resolution quantitative proteomics." (PMID 30024968, 2018). "pastoris protoplasts); in contrast, antibody binding to CD81 on the surface of human hepatoma cells was an excellent predictor of anti-viral potency." (PMID 29090272, 2017). "Introduction of L438V significantly decreased E1E2 fitness to mediate HCVpp or HCVcc entry into hepatoma cells, which is consistent with the observed reduction in binding of 1a154_L438V sE2 to CD81 and SR-B1." (PMID 28235087, 2017). "We demonstrate that antibody engagement of CD81 promotes hepatoma spread, which is limited by HCV infection, in an actin-dependent manner and identify an essential role for the C-terminal interaction with Ezrin-Radixin-Moesin (ERM) proteins in this process." (PMID 24662676, 2014). "In contrast, a Fab fragment of anti-CD81 clone 2s.66 failed to promote HepG2.CD81 spread, suggesting that changes in hepatoma morphology are dependent on antibody bivalency and CD81 cross-linking." (PMID 24662676, 2014). "CD81 expression promoted hepatoma invasion and migration, supporting a role for CD81 in hepatoma motility." (PMID 24662676, 2014). "CD81 localized at the plasma membrane of HepG2.CD81 cells and expression promoted hepatoma spread on anti-CD81 coated wells, whereas cells failed to attach or spread on isotype control IgG coated plates." (PMID 24662676, 2014). "Hepatoma cells expressing CD81ΔC displayed a significantly reduced ability to spread following CD81 ligation, suggesting an important role for the C-terminus in hepatoma morphology." (PMID 24662676, 2014). "A recent report showing that HCV infection reduces the expression of ERM proteins moesin and radixin provides an explanation for our observation that HCV infection limits CD81-dependent hepatoma spread." (PMID 24662676, 2014). "Antibody ligation of CD81 on Huh-7 hepatoma cells has been reported to activate the MAPK-ERK and Rho-family GTPase signaling pathways." (PMID 24662676, 2014). "In summary, these data support a role for CD81 in regulating hepatoma mobility and propose CD81 as a tumour promoter." (PMID 24662676, 2014).
hepatoma (continued). "Given the recent report that HCV infection reduces moesin expression we were interested to study the effect of HCV infection on CD81-dependent hepatoma spread." (PMID 24662676, 2014). "Given the limited and conflicting nature of these reports we investigated the role of CD81 in hepatoma biology." (PMID 24662676, 2014). "Both anti-CD81 and anti-Beta-1 integrin antibodies promoted hepatoma spread in a time dependent manner, whereas cells failed to attach or spread on isotype control IgG coated plates." (PMID 24662676, 2014). "Together, these data highlight a role for TNF-α in regulating hepatoma tight junction and CD81 dynamics, providing a mechanism for the increase in viral permissivity." (PMID 24259385, 2014). "We demonstrate that antibody engagement of CD81 induces hepatoma spread in an actin-dependent manner and identify a role for the C-terminus and Ezrin-Radixin-Moesin (ERM) proteins in this process." (PMID 24662676, 2014). "Given the role of hepatocellular CD81 in HCV infection and the association of chronic hepatitis C with hepatocellular carcinoma (HCC) there is a growing interest in studying the function of CD81 in hepatocytes." (PMID 24662676, 2014). "To study the processes involved in anti-CD81 induced hepatoma spread we adapted our assay to measure antibody-induced changes in hepatoma morphology by phase microscopy." (PMID 24662676, 2014). "The reduced spread of CD81-primed hepatoma cells following HCV infection demonstrates an indirect role for HCV to modulate hepatoma spread or metastasis." (PMID 24662676, 2014). "HepG2 cells, which naturally lack CD81, provide an ideal tool to evaluate CD81 specific changes in hepatoma morphology." (PMID 24662676, 2014). "Given our previous observation that anti-CD81 ligation promotes hepatoma spread, we measured the effect of anti-CD81 mAb on Huh-7.5 migration in the scratch wound assay." (PMID 24662676, 2014). "We show enhanced hepatoma migration and invasion following expression of CD81 and a reduction in invasive potential upon CD81 silencing." (PMID 24662676, 2014). "In summary, our data support a role for CD81 in regulating hepatoma mobility and implicate CD81 as a tumour promoter." (PMID 24662676, 2014). "Bivalent antibody ligation of CD81 is essential to promote the changes in hepatoma morphology, consistent with antibody induced cross-linking of CD81." (PMID 24662676, 2014). "Although CD81 is normally expressed at the surface of primary hepatocytes and most hepatoma cell lines, it has been observed that HepG2, HH29 cells and also some sub-clones of Huh-7 cells do not express this tetraspanin." (PMID 24509809, 2014). "We confirmed that anti-CD81 promoted the spread of Huh-7.5 hepatoma cells that naturally express CD81." (PMID 24662676, 2014). "In summary, these data support a role for CD81 dynamics in regulating HCV entry into hepatoma cells that is dependent on their polarized status." (PMID 23126643, 2013). "The principal new observations from these studies are that hepatoma polarization restricts CD81, lipid and HCVpp mobility, providing a mechanism to explain the limited HCV infection of polarized cells." (PMID 23126643, 2013). "Our data exhibited that HCVpp entry is blocked in hepatoma cell line with CD81 specific monoclonal antibody." (PMID 22074322, 2011). "We estimated that depending on the binding affinity of E2 and CD81, between 1 and 13 E2-CD81 complexes are necessary for HCVcc entry into human hepatoma-derived cells." (PMID 22174670, 2011). "Here, we have investigated the early events of IFN induction upon HCV infection, using the cell-cultured HCV JFH1 strain and the new HCV-permissive hepatoma-derived Huh7.25.CD81 cell subclone." (PMID 20485506, 2010). "Ectopic expression of EWI-2wint in a hepatoma cell line susceptible to HCV infection blocked viral entry by inhibiting the interaction between the HCV envelope glycoproteins and CD81." (PMID 18382656, 2008).